IL2 (interleukin 2)
Diseases named in the same sentence as IL2 in open-access papers (continued):
Sharing a sentence is not in itself a finding about the gene and the disease.
graft versus host disease (53 papers, 2012 to 2025). An immune system disorder that occurs after allogeneic hematopoietic stem cell transplant and is a reaction of donor immune cells against host tissues. "Independent from each other, two uncontrolled open-label trials investigated the clinical efficacy and safety of a low-dose IL-2 regimen with aldesleukin in patients with hepatitis C-associated vasculitis and graft-versus-host disease (GvHD), respectively." (PMID 33868284, 2021). "Low-dose recombinant human IL-2 expanded peripheral Tregs in vivo, beneficial to avert graft-versus-host disease (GvHD) in the process of cell transplantation (NCT00529035)." (PMID 39415291, 2024). "Prodigiosin also suppressed IL-2Rα expression in the IL-2/IL-2R signalling to block T-cell activation, inhibiting graft versus host disease (GvHD) and delayed the progression of autoimmune diabetes without toxicity in mice." (PMID 36577970, 2022). "Early clinical studies suggested that ld-IL-2 blocks the progression of graft-versus-host disease, systemic lupus erythematosus, and autoimmune hepatitis." (PMID 34324441, 2021). "In clinical trials, therapy with low-dose IL-2 for the treatment of graft versus host disease (GVHD) and T1DM appears to successfully expand the circulating Treg cell pool." (PMID 29805313, 2018). "Because NK expansion protocols frequently include factors such as high-dose IL-2, IL-15, and IL-21 that also stimulate proliferation of T cells, graft-versus-host disease is a particular concern." (PMID 29456538, 2018). "Low-dose IL-2 treatment of humans with graft-versus-host disease was originally found to lead to expansion of Treg cells and reduced symptoms in a group of patients." (PMID 29123649, 2017). "In the setting of bone marrow transplantation low-dose and very low-dose IL-2 have been shown to increase Treg cells, but their long-term value in preventing graft-versus-host disease (GVHD) is still being determined." (PMID 28848545, 2017). "In patients with either hepatitis C virus-induced vasculitis or graft versus host disease, treatment with low doses of IL-2 therapy increased Treg numbers and decreased clinical disease." (PMID 23029447, 2012). "Administration of low-dose IL-2, an essential cytokine for the maintenance and proliferation of Tregs, specifically expands Tregs in vivo and is a promising approach for treating autoimmune diseases and graft versus host disease (GVHD)." (PMID 38665907, 2024). "Similarly, IL-2 mediated augmentation of T-regs reduces skin fibrosis in some patients suffering from graft-versus-host disease (GVHD)." (PMID 36189219, 2022). "Such beneficial effects may be due to IL-2 dampening Th17 cells, which is hypothesized to be beneficial in graft-versus-host disease." (PMID 30598515, 2019). "However, monotherapy with IL-2 has been reported to increase Treg counts and limit the extent of graft-versus-host disease (GvHD) after allo-SCT in cancer patients, apparently without negatively affecting survival." (PMID 28721449, 2017). "The systemic administration of inflammatory cytokines such as IL-2 induces severe side effects related to T lymphocyte proliferation and activation, i.e., severe graft-versus-host disease (GvHD) or proliferation of regulatory T cells that decreases the GvL effect." (PMID 26320191, 2015). "Proleukin is a recombinant IL-2 traditionally used at high doses for cancer therapy that has recently been used with remarkable success at lower doses in graft-versus-host disease (GVHD) and hepatitis C-induced vasculitis with therapeutic responses correlating with increased Treg frequencies." (PMID 25457307, 2015). "We recently reported that anti-CD2-decorated nanoparticles (NPs) containing IL-2 prevent a fatal graft versus host disease (GVHD in humanized mice." (PMID 41368646, 2025).
graft versus host disease (continued). "Clinical trials in graft versus host disease (GVHD) and vasculitis using low-dose IL-2 as a stand-alone therapy for inflammatory and autoimmune conditions have already demonstrated increased Treg survival in these conditions and reduced disease activity." (PMID 30027532, 2018). "Moreover, humans with graft-versus-host disease receiving low-dose IL-2 treatment could be retrospectively divided into likely responders and non-responders based on PD-1 expression on their peripheral Treg cells." (PMID 29123649, 2017). "IL-2 has been tested in clinical trials to treat graft versus host disease (GVHD), hepatitis C virus-induced vasculitis, and T1DM through a Treg-dependent pathway." (PMID 26834735, 2015). "In clinical trials, low-dose IL-2 therapy has been investigated for the treatment of graft versus host disease (GVHD) and T1D and appears to successfully expand the circulating Treg cell pool." (PMID 25741338, 2015). "We also found that IL-1β, IL-2, IL-6 and IL-8 were significantly increased in episodes in which multiple viruses were simultaneously detected, and samples positive for EBV DNA and graft-versus-host disease had a further increase of IL-1β and IL-8." (PMID 36014102, 2022). "Two recent clinical studies showed that low-dose IL-2 administration had a therapeutic benefit in alleviating chronic graft versus host disease (GVHD) and chronic hepatitis C virus- (HCV-) mediated vasculitis by augmenting Treg cell counts and function without activating T effector cells." (PMID 27144181, 2016). "However, despite additional immune stimulation with G-CSF and occurrence of chronic graft versus host disease (GvHD) the patient relapsed, with the relapsed disease being insensitive to further immune stimulation with IL-2 and natural killer cell infusion." (PMID 24860670, 2014). "We have previously reported that the treatment of mice with poly(lactic-co-glycolic) acid (PLGA) nanoparticles (NPs) decorated with anti-CD2 antibodies and encapsulating IL-2 and TGF-β induced tolerogenic CD4+ and CD8+ pTregs that protected mice from fatal graft-versus-host disease (GvHD)." (PMID 40799646, 2025). "Low-dose interleukin-2 (Ld-IL2) therapy emerges as a promising new therapy to treat a wide range of inflammatory, autoimmune and alloimmune disorders such as SLE, hepatitis C-induced vasculitis, graft-versus-host disease (GVHD)." (PMID 34618873, 2021). "In 10 pediatric patients, complete remissions (CRs) were achieved by KIR ligand-mismatched CD3-depleted and CD56-enriched NK cells (median dose, 26 × 106/kg) and six doses of IL-2 (1 million U/m2) without graft versus host disease (GVHD) and remained in CR for 2 years." (PMID 34572387, 2021). "NFAT could enhance the expression of IL-2, an important mediator of graft-versus-host disease, under the stimulation of T cells, while cyclosporine A (CsA) acted as an immunosuppressive agent by reducing the nuclear accumulation of NFAT and then IL-2 expression." (PMID 35957916, 2022). "Finally, treosulfan was shown to reduce lymphocyte counts for longer periods, resulting in suppressed cytokine production (specifically, IL-2 and INF-γ), which is involved in the development of subsequent graft versus host disease (GvHD)." (PMID 35205772, 2022).
Granuloma (53 papers, 2006 to 2025). A compact, organized collection of mature mononuclear phagocytes, which may be but is not necessarily accompanied by accessory features such as necrosis. "Granulomas from high-risk animals had higher frequencies of IL-17, IL-10 or IL-2 producing CD3+ T cells as compared to granulomas from low risk animals." (PMID 27379816, 2016). "In our study, granulomas that had a higher proportion of T cells producing IL-10 in combination with T cells producing pro-inflammatory cytokines IL-2, TNF or IL-17 were associated with sterilization." (PMID 25611466, 2015). "More studies should be conducted to investigate whether the observed increases in cytokines IFN-γ, TNF-α, IL-2, and decrease in IL-10 found in granuloma supernatants is indeed the cause of the decreased burden of mycobacterial." (PMID 34150674, 2021). "The significantly greater amounts of IL-2 detected in the blood of mice immunized with Sm16/Freund's may be associated with the increased granuloma area observed in animals receiving this vaccine formulation." (PMID 31886307, 2019). "IL-2, an important cytokine, plays a crucial role in inducing T-cell proliferation, generating cell-mediated immune responses, and contributing to granuloma formation in TB disease." (PMID 40622143, 2025). "From this point on, the T cells are the ones pathologically dictating the creation of the granuloma, releasing the highly granuloma-associated conception cytokines IFN-γ, IL-17A and IL-2, leading to the circulation of other cell types." (PMID 40002701, 2025). "Using a human granuloma model, we showed the addition of either exogenous IL-17 or IL-2 enhanced immune control of M. tuberculosis and was associated with increased NO production." (PMID 33848273, 2021). "L-GSH supplementation was also able to modulate cytokines levels of IFN-γ, TNF-α, and IL-2 within in vitro granulomas treated with everolimus." (PMID 33966361, 2021). "For example, there were 5 granulomas binned at bin 3/3 for IL-2 and IFN-γ cytokine combinations respectively, of which 4 granulomas were sterile and 1 grew Mtb (non-sterile)." (PMID 25611466, 2015). "We also demonstrated that the Th1 cytokines, IFN-γ and IL-2, were detected in early granulomas, while Th2 cytokines, IL-4 and IL-10, were detected in more mature granulomas." (PMID 25530957, 2014). "TB granulomas were seen in lung tissue sections from all IL2-treated macaques although these animals were less necrotic than saline/BSA-treated group." (PMID 23966854, 2013). "Using a commercial kit to detect typical Th1/Th2 cytokines, we compared the levels of IFN-γ, TNF-α, IL-2, IL-4, and IL-5 in lung homogenates 14 days after granuloma induction and in serum samples collected 1, 5, 14 and 18 days after granuloma induction." (PMID 22013486, 2012). "CD11c+ cells purified from three-week granulomas were more efficient at inducing IFNγ and IL-2 production from OT-II CD4+ T-cells than CD11c+ cells from ten-week granulomas." (PMID 20625513, 2010). "A low level of IL-5 mRNA expression was detectable in all granulomas as was the level of IL-2 expression." (PMID 16542426, 2006). "This spatial model accounted for granulomas as evolving regions over time and incorporated variables such as the density of macrophages, Treg, Th1, and Th17 cells, as well as concentrations of IL-2, IL-10, IL-12, IL-13, IFN-γ, TNF-α, TGF-β, GM-CSF, and CCL20, along with fluid velocity." (PMID 39996765, 2025). "Exogenous IL-17 and IL-2 are protective in a functional 3D granuloma model." (PMID 33848273, 2021). "Another important cytokine involved in the genesis of granuloma is IL-2." (PMID 31886307, 2019). "There were T cells present that were producing both TNF and IL-2 in a subset of granulomas." (PMID 25611466, 2015).
Granuloma (continued). "Moreover, infected KO rats displayed a marked decrease in the levels of both Th1- (IFN-γ) and Th2-associated cytokines (IL-4, IL-5) at all time points post-infection, except with IL-2 and IL-13, both of which play an important role in granuloma and fibrosis development." (PMID 35584107, 2022). "Instead, the proportion of CD8α− γδ T cells in granulomas increased and had similar function as CD8α+ γδ T cells, thereby replacing production of IFN-γ, TNF, IL-2, and/or IL-17." (PMID 39912921, 2025). "These cells secrete pro-inflammatory cytokines, including interferon-γ (IFN-γ), interleukin-2 (IL-2), and tumor necrosis factor-α (TNF-α), which mediate local granuloma development." (PMID 37062818, 2023). "Nevertheless, sterile granulomas had modestly higher TNF (p = 0.0091), IL-17 (p = 0.0344) and T-1/T-17 (CD3+ T cells producing single or combinations of IFN-γ, IL-2, TNF, or IL-17 cytokines) (p = 0.0273) cytokine producing T cells than non-sterile granulomas." (PMID 25611466, 2015). "CD4+ T cells interact with antigen presenting cells which initiate the formation and maintenance of granulomas, resulting in differentiation of selective Th1 cells secreting IFN-γ and IL-2." (PMID 23320239, 2012). "Granuloma formation occurs through activation of CD4-positive T cells and macrophages against unidentified antigens, resulting in the release of cytokines such as interleukin-2, interferon-γ, and tumour-necrosis-factor-α." (PMID 41541976, 2025). "Immune and parenchymal cells in granuloma-rich right lungs demonstrated robust upregulation of genes related to immune activation, chemokine/cytokine signaling, and antimicrobial defense (CXCL, CCR, IL2, IRF4, GZMK)." (PMID 41586350, 2025). "In contrast, ZOL/IL2-treated (Group-2) and IL2-treated (Group-3) macaques generally showed small non-necrotic or less-necrotic granulomas, and localized or contained by large numbers of lymphocytes as pointed by small black arrows." (PMID 35765887, 2022). "At that time, stimulated-liver tissue or isolated granulomas from infected mice failed to produce IL-2." (PMID 34161342, 2021). "The granulomatous reaction to Beryllium is caused by the activation of CD4+ lymphocytes that recognize Beryllium and produce IL-2 and IFN gamma, activating the multinucleated phagocytes and starting the formation of granulomas in the interstitium and in the pulmonary lymph nodes." (PMID 35011621, 2021). "Furthermore, inflammatory cytokines, which present high levels at the beginning of granuloma formation, such as IFN-ɣ, IL-2, IL-4, MCP-1, and TNF-α, are important factors in reducing the spread of the bacteria." (PMID 34843474, 2021). "The formation of glial nodules might be due to the chitin of endospore microsporidians as chitin is chemotactic for macrophages and results in the recruitment of CD8+ cells, production of IL-2 and IFN-γ, which eventually lead to formation of granulomas." (PMID 32087749, 2020). "However, it has been suggested that cytokines including IL-2, IL-7, IL-8, IL-12, IFN-γ, TNF-α, and GM-CSF have an important role in initiation and continuation of granuloma formation." (PMID 32350353, 2020). "Of note, LNs with granulomas that are sterile had significantly higher frequencies of CD3+ T cells producing IFNγ; CD8+ cytotoxic T cells producing IFNγ, IL-2 or TNF and CD20+ B cells producing IL-2 than CFU+ LNs." (PMID 30383808, 2018). "Granuloma formation also requires the presence of TNF, IL-2, IL-12, and inflammatory cytokines, such as monocyte chemotactic protein-1(MCP-1), and macrophage inflammatory protein-α (MIP-α), which collectively are involved in recruiting host cells to the site of infection leading to inflammation." (PMID 19946453, 2009).
Granuloma (continued). "Using the lung biochip integrated with the granuloma model developed by Calcagno and colleagues, researchers have demonstrated that α-MSH significantly reduces key inflammatory cytokines, including IL-1β, GM-CSF, type I IFN cytokines (ISG15 and IFN-α), and IL-2 compared with untreated controls." (PMID 39996765, 2025). "Of particular interest was the observation that the innate granulomas (both uninfected [UIG] and BCG-infected [IIG]) did not produce high levels of cytokines like TNF-α, IFN-γ, and IL-2 associated with T cell production and release, further supporting the previous statement." (PMID 34287004, 2021). "Importantly, IL-17, TNF-α, and/or multi-functional T cells (IFN-γ+IL-2+TNF+ T cells) were observed at higher frequencies in sterile granulomas than in non-sterile granulomas." (PMID 26675186, 2015). "IL-2 was detected in the same level in lung homogenates of normal and experimental groups, and the low levels of IL-4 detected in lung homogenates of immune and tolerant mice did not correlate with the size of their granulomas." (PMID 22013486, 2012). "However, LBR5, LBR6 and LBR8 induced increased levels of pro-inflammatory cytokines (IFN-γ, IL-2, IL-6, TNF-α and IL-17A), which are consistent with a robust Th1 immune response that especially promotes cellular proliferation and the formation of granulomas (IFN-γ and TNF-α)." (PMID 34046037, 2021). "Although the responses generally overlapped, sterile granulomas had modestly higher frequencies of T cells making IL-17, TNF and any of T-1 (IFN-γ, IL-2, or TNF) and/or T-17 (IL-17) cytokines than non-sterile granulomas." (PMID 25611466, 2015). "In other five Picostim/IL2-treated macaques, microscopic TB granulomas were smaller, more focal and much less necrotic than those in the saline/BSA-treated macaques, and similarly non-necrotic or more lymphocytic compared to IL2-treated macaques." (PMID 23966854, 2013).